IL13 (interleukin 13)
Diseases named in the same sentence as IL13 in open-access papers (continued):
Sharing a sentence is not in itself a finding about the gene and the disease.
pulmonary fibrosis (continued). "Having shown that P. aeruginosa infection induces a specific antibody against PE, we next determined whether this prior infection altered the efficacy of IL13-PE therapy in a pulmonary fibrosis model induced by the intratracheal introduction of bleomycin sulfate." (PMID 20090941, 2010). "Next, levels of IL-4, IL-13 and TGF-β1 in BALF of WT and USP25-/-mice after BLM-induced pulmonary fibrosis models were measured by ELISA." (PMID 39781451, 2025). "The authors explored the efficacy of four therapies (anti-TNF-α, anti-PDGF, anti-IL13, anti-TGF-β) and showed that only targeting TGF-β should result in a beneficial effect on pulmonary fibrosis." (PMID 38550585, 2024). "The pathogenesis of pulmonary fibrosis involves various mediators such as TGF-β, legumain, osteopontin, IL-4, IL-6, IL-13, IL-17, TNF-α, Gal-1, Gal-3, PDGF, and FGFR-1." (PMID 38540252, 2024). "Benchmarking the effect of cytokine-targeting drugs (anti-TNF-α, anti-PDGF, anti-IL-13, anti-TGF-β) on pulmonary fibrosis progression." (PMID 38550585, 2024). "A relationship was also observed between the markers of progression to pulmonary fibrosis (i.e., YKL-40 and KL-6), IL-6, IL-10, and IL-13 cytokines and mortality." (PMID 36975498, 2023). "In a bleomycin-induced pulmonary fibrosis model, CD8+ T cells were shown to differentiate into profibrotic IL-13-producing cells." (PMID 36930615, 2023). "This was further confirmed by their following experiments which showed that transfer of IL‐13+ILC2 significantly potentiated collagen deposition, and further amplified lung fibrosis induced by S. mansoni egg." (PMID 36082495, 2022). "MMP9 was also an essential player in IL-13 mediating TGF-β1 secretion and was involved in pulmonary fibrosis and degradation of extracellular matrix." (PMID 35912246, 2022). "According to the existing studies, the development of pulmonary fibrosis in the patients with SARS-CoV-2 infection is accompanied by the increased expression of cytokines such as TGF-β, TNF-α, IL-1β, IL-6 and IL-13." (PMID 34876129, 2021). "Some studies have pointed out that IL-13 would also drive the expression of TGF-β, exacerbating lung fibrosis." (PMID 34070405, 2021). "In this study, bleomycin-induced pulmonary fibrosis was characterized by increases in CTGF, TGFβ1, ET-1, IL-6, and IL-13, as profibrotic mediators." (PMID 29409529, 2018). "In this context, an interplay between ILC, macrophages, and cells of the adaptive immune system was shown to participate—together with IL-13, IL-25, and IL-33—in the pathogenesis of BLM-induced pulmonary fibrosis in mice." (PMID 28018357, 2016). "Next, expressions of the fibrosis-related genes IL-13 and TGF-β during silica-induced lung fibrosis were evaluated by real time PCR analysis." (PMID 27354007, 2016). "The classic profibrotic cytokine IL-13 reduced the levels of many inflammatory cytokines and induced TGF-β signaling, which was essential in lung fibrosis." (PMID 27354007, 2016). "In animal models pulmonary overexpression of IL-13 induced subepithelial airway fibrosis; its inhibition with anti-IL-13 antibody significantly reduced ECM deposition after bleomycin-induced lung fibrosis." (PMID 26199463, 2015). "We also examined the levels of several other classical cytokines (including IFN-γ, IL-4, IL-12, IL-13) and several matrixmetalloproteinases (such as MMP2, MMP9) in this model of lung fibrosis." (PMID 26627341, 2015). "However, it is unclear whether YY1 is an essential mediator of IL-13-induced lung fibrosis." (PMID 25775215, 2015). "Other cytokines, such as connective tissue growth factor (CTGF), interleukin-4 (IL-4), interleukin-13 (IL-13) and endothelin etc., can cooperate with TGF-β to promote MF generation or proliferation, which, therefore, leads to pulmonary fibrosis." (PMID 24584660, 2014). "It has been found that MMP9 levels are elevated in patients with pulmonary fibrosis and furthermore, ablation of the MMP9 gene reduces IL-13-dependent lung remodelling." (PMID 22205929, 2011).
pulmonary fibrosis (continued). "In the rat study investigating the effects of Ole on pulmonary fibrosis induced by intratracheal bleomycin, TNF-α, IL-13, TGFβ1, Platelet-derived growth factor (PDFG), lung collagen index and MDA increased significantly in BALF, but Ole prevented pulmonary fibrosis by reversing these effects." (PMID 40233022, 2025). "Notably, MUC5B rs35705950 TG mice with lung fibrosis exhibited markedly reduced PDGF, CTGF, and IL-13 levels compared to their WT counterparts." (PMID 39329706, 2024). "In 2018, news studies showed that S1PR2 might also affect pulmonary fibrosis on a transcriptional level; S1PR2 deletion reduced the expression of profibrotic cytokines such as IL-13 and IL-4 in bleomycin-induced pulmonary fibrosis." (PMID 37371823, 2023). "Previous studies have found that IL-13 signals through IL-13R2 to induce transforming growth factor beta (TGF-β) and fibrosis progression, and silencing of IL-13Rα2 reduced TGF-β production and lung fibrosis." (PMID 36685820, 2022). "This study in a pulmonary fibrosis mice model found that ILC2s secreted IL-13 in an IL-25-dependent manner, which was independent of the antigen-specific immune responses mediated by CD4+T cells." (PMID 35592688, 2022). "By contrast, mIL‐33 may potentiate lung fibrosis by recruiting ST2L+M2‐macrophages and ST2L+ILC2s to enlarge Th2 cytokine milieu by excessive production of IL‐4, IL‐5, and IL‐13." (PMID 36082495, 2022). "IL-13 secretion by Mφs has not been previously reported under physiological conditions, only in the context of pulmonary fibrosis." (PMID 35488301, 2022). "Nonetheless, IL-13 seems to be the main fibrotic driver as on the one hand overexpression of IL-13 but not IL-4 induces spontaneous lung fibrosis and on the other hand IL-13-/- mice but not IL4-/- are protected from FITC-related fibrosis." (PMID 34093523, 2021). "All these indicate that TGF-β, TNF-α, IL-1β, IL-6, IL-13, ACE2 and autophagy inhibition may be the key factors in pulmonary fibrosis induced by SARS-CoV-2." (PMID 34876129, 2021). "For instance, IL-13 is required for fibrotic changes in the lung after Schistosoma mansoni egg challenge but not in the bleomycin model of pulmonary fibrosis." (PMID 34127548, 2021). "Exposure of these cells to IL-13 results in impaired AEC1 differentiation and development of a bronchiolar transcriptomic phenotype aside from increased in vitro apoptosis, potentially affecting the development of lung fibrosis." (PMID 34093523, 2021). "In summary, our data imply that an increased MSR1, IL-13, and Arg1 expression occurs in patients with IPF, an observation that could suggest a possible role for M2 macrophages in the pathogenesis of pulmonary fibrosis." (PMID 33604393, 2021). "Notably, it remains to be seen whether the pro-fibrotic activity of IL-13 is of clinically high enough relevance to render a vaccination treatment effective in several conditions involving increased fibrosis (e.g. hepatic fibrosis, pulmonary fibrosis due to various etiologies)." (PMID 30759882, 2019). "Thus, S1PR2 facilitates lung fibrosis through the mechanisms involving augmentation of IL-13 expression and its signaling in BALF cells, and represents a novel target for treating lung fibrosis." (PMID 29782549, 2018). "Consistent with an independent role of p-JAK2 in lung fibrosis, we observed that p-JAK2 inhibition in ATII and lung fibroblasts from IPF patients partially reduced the mesenchymal-myofibroblast transformation induced by TGF-β1 and IL-6/IL-13." (PMID 29409529, 2018). "Thus, Akt2 regulates pulmonary fibrosis by up-regulating the pro-fibrotic TGF-β and IL-13 production by macrophages." (PMID 30405626, 2018). "Indeed, Th1 cells can produce IL-13 under chronic stimulation, in the presence of TGF-β whereas, in lung fibrosis, Th2 cells can produce IL-935." (PMID 28900244, 2017).
pulmonary fibrosis (continued). "This is in line with data in which IL-13 KO mice are protected from lung fibrosis but not IL-4 KO mice, despite the fact that they have abundant TGF-β1 levels." (PMID 27113293, 2016). "IL-13, IL-4 and IFN-γ were not significantly different in the myeloid PTEN deficient mice subjected to pulmonary fibrosis." (PMID 26971883, 2016). "Reduced IL-13 was unable to promote the expression of TGF-β and its signaling pathway, which might attenuate lung fibrosis." (PMID 27354007, 2016). "While IFN-γ is known to inhibit fibrosis, IL-5 may promote pulmonary fibrosis by its effect on recruiting eosinophils and the subsequent production of TGF-β1, PDGF, and IL-13." (PMID 25944985, 2015). "In contrast, IL-13 and MCP-1 contribute to the development of BLM-induced lung fibrosis." (PMID 26289430, 2015). "Prior sensitization to IL13-PE protected bleomycin-challenged mice from mortality but not from pulmonary fibrosis (saline + PE group)." (PMID 20090941, 2010). "Taken together, our results suggest that prior patient exposure to Pseudomonas or immunity directed against its exotoxin does not diminish the therapeutic potential of IL13-PE in the treatment of pulmonary fibrosis." (PMID 20090941, 2010). "However, MMP-9 activity to regulate the lung fibrosis response is cell-specific; MMP-9 did not affect the lung fibrosis response in transgenic mice overexpressing profibrotic interleukin (IL)-13 in airway club cells." (PMID 36834561, 2023). "Therefore, we speculate that fucoxanthin improves pulmonary fibrosis and AHR in asthmatic mice by reducing the activity of IL-13." (PMID 34070405, 2021). "Despite the fact that overwhelming evidence exists regarding the role of type 2 immunity in lung fibrosis, these findings should be contrasted with the disappointing results of therapeutic trials of IL-13 and dual IL-4/IL-13 inhibition in IPF, which both failed to meet their therapeutic endpoints." (PMID 34093523, 2021). "In the bleomycin-induced mouse pulmonary fibrosis model, IL-4 and IL-13 levels were significantly increased, but after blocking the IL-4/IL-13 signaling pathway, the activation of STAT6 was reduced and which could significantly ameliorate pulmonary fibrosis." (PMID 34594474, 2021). "In brief, actions of some of the assessed interleukins in the context of pulmonary fibrosis can be summarized as follows: IL1ꞵ (pro-fibrotic), IL4 (pro and anti-fibrotic), IL6 (pro and anti-fibrotic), IL8 (pro-fibrotic), IL10 (anti-fibrotic), IL12 (anti-fibrotic), and IL13 (pro-fibrotic)." (PMID 34960806, 2021). "Our previous studies demonstrate upregulation of multiple growth factors including TGFβ, IL-6, IL-13, amphiregulin and epiregulin in distinct mesenchymal cell subsets such as fibrocytes, lung resident fibroblasts and WT1-positive myofibroblasts during TGFα-induced pulmonary fibrosis." (PMID 31156440, 2019). "In addition, no induction of liver or lung fibrosis due to the continuous IL-13 injection was observed (unpublished observations)." (PMID 23027612, 2012). "Thus, using a well-established bleomycin pulmonary fibrosis model, we have observed that prior Pseudmonas infection or systemic sensitization to IL13-PE does not impair the therapeutic anti-fibrotic properties of IL13-PE." (PMID 20090941, 2010). "Because IL-13 protein levels were similar in BALFs of wild-type and S1pr2-/- mice, these observations suggest that S1PR2 may be involved in lung fibrosis mainly through potentiating cellular responses to the key profibrotic mediator IL-13 rather than stimulating the production of IL-13 in lung." (PMID 29782549, 2018). "The IL-13 in the model group was higher than that in the sham group and number 2 FBR group, indicating that the infusion of PM2.5 in the airway could increase the inflammation and promote the excessive secretion of mucus and lead to significant pulmonary fibrosis." (PMID 29541141, 2018). "However, it is not known whether PI3K/AKT signaling is involved in IL-13-induced lung fibrosis." (PMID 25775215, 2015).
pulmonary fibrosis (continued). "For example, V2O5-induced lung fibrosis in mice features Th1 inflammation and elevated levels of interferon-γ (IFN-γ) and IFN-inducible cytokines along with elevated levels of profibrogenic growth factors (PDGF-CC, CTGF, TGF-β1) and collagen with no apparent increases in IL-13." (PMID 20738867, 2010).
COVID-19 (163 papers, 2020 to 2026). A disease caused by infection with severe acute respiratory syndrome coronavirus 2. "Elevated levels of IL-4 and IL-13, key cytokines associated with AD, have been linked to more severe COVID-19 outcomes." (PMID 40438776, 2025). "In our previous work we implicated type 2 immune pathways and the cytokine IL-13 as key drivers of COVID-19 pathogenesis upstream of HA deposition." (PMID 41279061, 2025). "In the context of SARS-CoV-2 infection, IL-13 has been implicated in driving severe COVID-19 outcomes by exacerbating airway inflammation, increasing mucus production, and promoting immune cell recruitment." (PMID 40149651, 2025). "Elevated IL-13 has been previously associated with severe COVID-19 outcomes, including the need for mechanical ventilation." (PMID 40867589, 2025). "IL-13 is elevated in severe COVID-19 patients requiring mechanical ventilation and is linked to poor outcomes." (PMID 40943354, 2025). "A hallmark of early COVID-19 is an increase in pro-inflammatory cytokines, especially IL-6 and TNFα, as well as IL-1 β, IL-8, GM-CSF, and the type 2 inflammatory cytokine IL-13." (PMID 39000027, 2024). "IL-6 and TNFα are central to the inflammatory response in COVID-19, and IL-13 has also been linked to disease severity, driving increased levels of eosinophils and macrophages in the lungs and stimulating smooth muscle hypertrophy and fibrosis." (PMID 39000027, 2024). "The release of IL-4 and IL-13 from Th2 cells is considered an important factor for low ventilation and death associated with COVID-19 and these cytokines are targets for immunotherapy agents such as dupilumab." (PMID 39257580, 2024). "Within this set, there are several immune-related processes known to be implicated in COVID-19 severity such as ‘Interleukin-5 and interleukin-13 signalling’ and ‘Caspase activation via death receptors in the presence of ligand’." (PMID 38527092, 2024). "We have discovered that high plasma interleukin (IL)–13 is associated with COVID-19–induced respiratory failure, a finding further validated in other COVID-19 observational studies." (PMID 38312212, 2024). "Since IL-13 causes the severity of COVID-19 and alters crucial biological processes, it is urgent to explore novel molecules capable of modulating IL-13." (PMID 39172871, 2024). "Since IL-13 causes the severity of COVID-19 and alters crucial biological processes, it is urgent to explore novel molecules or peptides capable of including IL-13." (PMID 39172871, 2024). "Th2 cells from people with PCC presented high capacity to express IL-4 and IL-13, which are related to low ventilation and death associated with COVID-19." (PMID 39257580, 2024). "Increased BAL IL-13, IL-5, and eotaxin at day 5 suggest increased activation and recruitment of eosinophils which have been implicated in COVID-19 pathogenesis." (PMID 38259435, 2023). "Recently, studies have reported that elevated levels of IL-13 are associated with the severity of COVID-19." (PMID 37568438, 2023). "In another study, transplantation of MSCs in COVID-19 patients was associated with a significant increase in anti-inflammatory cytokines (IL-10, IL-13) and also a significant decrease in pro-inflammatory cytokines, i.e., IFN-γ, IL-6." (PMID 37365605, 2023). "Interleukin (IL)-13 is one of the cytokines that has been recently associated as drivers of COVID-19 severity." (PMID 37041520, 2023). "As for IL-13, recently published studies also demonstrated the association of this cytokine with severe outcomes in patients with COVID-19." (PMID 36975498, 2023). "Within the COVID-19 group, IL-1β, IL-8, IL-13, and TNF were negatively associated whereas IL-12, GM-CSF and bFGF were positively associated with days since symptom onset/positive test." (PMID 35222429, 2022). "For example, severe COVID-19 was linked to changes in IL-13, IL6 and IL-1B, and multiple chemokines (e.g. CCL20, CCL27, CXCL10)." (PMID 36171541, 2022).
COVID-19 (continued). "In this study, we characterized the immune response of patients with COVID-19 and identified the type 2 cytokine, IL-13, as associated with severe outcomes." (PMID 34185704, 2021). "Because increases in HA have been observed in patients with COVID-19, this study provides a potential link between the association of IL-13 with severe disease and increased HA seen in other studies." (PMID 34185704, 2021). "To further investigate how IL-13 neutralization protected from COVID-19, we assessed expression of the type 2 associated proteins Ym1 and RELMα." (PMID 34185704, 2021). "The IL-13 blocking drug, Dupilumab, in turn, is associated with better outcomes in patients with COVID-19." (PMID 34185704, 2021). "Since coronavirus disease 2019 (COVID-19) is fundamentally characterized by dysregulation of the lung mucosae, we postulate that IL-13 is associated with destructive lung hyperinflammation/immune activity that underpins severe COVID-19 disease progression." (PMID 34027204, 2021). "By inhibiting IL-13 signaling, dupilumab may help mitigate these pathogenic processes, thereby reducing disease severity in COVID-19 patients." (PMID 40149651, 2025). "Indeed, IL-13 signaling has been linked to the regulation of hyaluronic acid and the persistence of post-COVID-19 conditions." (PMID 40429886, 2025). "Severe COVID-19 seems to correlate with an early defective Th1 response linked to an increased Th2 response in the context of a cytokine dysregulation, with an increase in interleukin (IL)-13, IL-5, eotaxin-2, IgE, and eosinophils." (PMID 38541703, 2024). "The increased levels and potential pathogenic effects of IL-4 and IL-13 in AD and COVID-19 suggest that blockades against IL-4/13 may be of some benefit for AD patients infected with SARS-CoV-2." (PMID 37240520, 2023). "Interestingly, the recent association of IL-13 with COVID-19 severity has sparked interest in this cytokine." (PMID 37041520, 2023). "In another retrospective analysis using a large COVID-19 international cohort, people who had been receiving treatment for severe asthma with Dupilumab, a monoclonal antibody that blocks IL-13 and IL-4 signalling, demonstrated a lower risk of ventilation and death from COVID-19." (PMID 36851616, 2023). "This is, somehow, in contrast to the previously demonstrated protective role of exogenous IL-13 in rodent models of LPS-induced endotoxemia that shares some similar immunopathogenetic mechanisms as SARS-CoV-2 pneumonitis." (PMID 37568438, 2023). "Recently, IL-13 was reported to be associated with the severity of COVID-19." (PMID 37041520, 2023). "Given that IL-4 and IL-13 targeted by dupilumab are Th-2 cytokines, their signaling pathways have not been classically implicated in the cytokine storm typifying severe advanced COVID-19." (PMID 34647194, 2022). "IL-13 is associated with severe COVID-19 in 2 patient cohorts." (PMID 34185704, 2021). "Here, we have shown that the type 2 cytokine, IL-13, is associated with severe COVID-19." (PMID 34185704, 2021). "The presence of AAMs, or similarly characterized macrophages, has been observed in patients with severe disease, together suggesting that IL-13 may promote these cells as a pathogenic mediator for disease and potentially longer-term pathology associated with long COVID-19." (PMID 34185704, 2021). "This analysis shows that several inflammatory and viral cytokines remain elevated beyond the acute phase and are associated with cognitive deficits, including IL-6, IL-13, IL-8, IL-1β, TNFα, and MCP1 in long-term post-COVID-19 patients." (PMID 41516418, 2026). "IL-13 can be expressed in COVID-19 patients, and levels correlate with the likelihood of requiring a ventilator once hospitalized." (PMID 40854598, 2025).